CDKN3 (cyclin dependent kinase inhibitor 3)
Description:
May play a role in cell cycle regulation. Dual specificity CC phosphatase active toward substrates containing either phosphotyrosine or phosphoserine residues. Dephosphorylates CDK2 at 'Thr-160' in a cyclin-dependent manner.
Synonyms: CDI1; CIP2; KAP; KAP1
Tractability: Small molecule: a structure with a bound ligand is known. PROTAC: ubiquitination databases record sites on it.
Gene: Protein-coding gene on chromosome 14 (54,396,849 to 54,420,218, forward strand). Ensembl gene ENSG00000100526.
Subcellular location: Cytoplasm, perinuclear region
Subcellular location (Human Protein Atlas): Cytosol
Gene Ontology:
Molecular function: protein binding; protein serine/threonine phosphatase activity; protein tyrosine phosphatase activity; protein tyrosine/serine/threonine phosphatase activity; phosphoprotein phosphatase activity
Biological process: regulation of cell cycle; G1/S transition of mitotic cell cycle; negative regulation of cell population proliferation; regulation of cyclin-dependent protein serine/threonine kinase activity
Cellular component: cytosol; perinuclear region of cytoplasm; cytoplasm; nucleus
Genetic constraint (gnomAD): Loss-of-function variants: 2 observed, 5.58 expected, observed/expected ratio (o/e) 0.36, 90% interval 0.14 to 1.12. That is too few expected variants to judge how well the gene tolerates losing a copy. Missense variants: 58 observed, 86.31 expected, observed/expected ratio (o/e) 0.67, 90% interval 0.54 to 0.84. Synonymous variants: 22 observed, 28.23 expected, observed/expected ratio (o/e) 0.78, 90% interval 0.56 to 1.11.
Homologues: Orthologues: macaque CDKN3 (99% identical), chimpanzee CDKN3 (99% identical), dog CDKN3 (92% identical), mouse Cdkn3 (89% identical), rat Cdkn3 (89% identical), guinea pig CDKN3 (87% identical), pig CDKN3 (81% identical), rabbit CDKN3 (71% identical), zebrafish cdkn3 (58% identical). Paralogues in human: CDC14A (23% identical), CDC14B (21% identical), PTPDC1 (20% identical), PTP4A1 (20% identical), CDC14C (19% identical), PTP4A2 (19% identical), PTP4A3 (19% identical), PALD1 (17% identical).
Diseases named in the same sentence as CDKN3 in open-access papers:
CDKN3 is named in the same sentence as 110 diseases in open-access papers, as found by Europe PMC text mining. Sharing a sentence is not in itself a finding about the gene and the disease. The quoted sentences say what the papers report.
breast cancer (24 papers, 2006 to 2024). A primary or metastatic malignant neoplasm involving the breast. "In another breast cancer study using gene expression and copy-number alterations data in a neural network-based approach, the CDKN3 was one of the subtype-specific genes identified belonging to the LumA subtype." (PMID 37489460, 2023). "At present, evidence of the relationship between RRM2 and CDKN3 in cervical cancer is limited, but their relationship can be found in other cancers, such as hepatocellular carcinoma, breast cancer, renal carcinoma and lung cancer 51-54." (PMID 32922202, 2020). "CDKN3 had been overexpressed frequently in several types of cancers, such as breast cancer, prostate cancer, and HCC." (PMID 31043166, 2019). "However, there are not many relative researches about CDKN3 in breast cancer." (PMID 31777591, 2019).
prostate carcinoma (18 papers, 2008 to 2024). A carcinoma that arises from epithelial cells of the prostate gland. "Despite the negative regulatory effects of CDKN3 on CDK1 and CDK2, an oncogenic role for aberrant overexpression of CDKN3 has been implicated in numerous types of human cancer, including prostate cancer, gastric cancer, nasopharyngeal carcinoma, and esophageal cancer." (PMID 33468140, 2021). "By controlling the cell cycle and DNA replication signals, cyclin-dependent kinase inhibitor 3 (CDKN3) is a key player in the development of prostate cancer." (PMID 36499614, 2022). "These represented cell cycle/mitosis; among others CCNE1, CCNE2, CCNG2, CCNL1, CCNT1, CDK12 and CDKN3, prostate cancer; including the androgen receptor (AR), metabolism as well as targets of the transcription factors E2F, AP2, SP1, ETF and Pax3." (PMID 26698305, 2015). "Contradictorily, CDKN3 is highly expressed in breast and prostate cancers, and blocking CDKN3 expression can inhibit the transformation." (PMID 25360622, 2014). "Association of LGALS3 (lectin, galactoside-binding soluble 3) is reported with endometrial, breast and colorectal cancer, and CDKN3 (cyclin-dependent kinase inhibitor 3) is known to be involved in hepatocarcinogenesis and breast and prostate cancer development." (PMID 21708004, 2011). "Similarly, cyclin dependent kinase inhibitor 3 (CDKN3) is overexpressed in prostate cancer, and its inhibition enhances apoptosis and promotes G1 cell cycle arrest by reducing the expression of cell cycle and DNA replication proteins, inhibiting cancer cell growth and invasion." (PMID 38848146, 2024). "Similarly, overexpression of TOP2A was associated with advance histological grading, vascular invasion, and an early age onset of HCC, while CDKN3 was reported as part of a vascular invasion signature in HCC and has been implicated in other malignancies including breast and prostate cancers." (PMID 22539975, 2012). "UBE2C, PDZ-binding kinase (PBK), cyclin B1 (CCNB1), Cyclin-dependent kinase inhibitor 3 (CDKN3), topoisomerase II alpha (TOP2A), Aurora kinase A (AURKA) and MKI67 were identified as the candidate hub genes, which were all correlated with prostate cancer patient’ disease-free survival in TCGA." (PMID 33630978, 2021). "The results showed that 7 genes were all associated with prostate cancer prognosis, but only UBE2C, TOP2A and CCNB1 were high expression in prostate cancer samples than normal prostate gland samples, the expression of PBK, CDKN3, AURKA, MKI67 were not." (PMID 33630978, 2021).
lung adenocarcinoma (17 papers, 2013 to 2025). A carcinoma that arises from the lung and is characterized by the presence of malignant glandular epithelial cells. "CDKN3 encodes a cyclin inhibitor (regulating cell cycle) and has been described as being overexpressed in lung adenocarcinoma (ADC), squamous cell carcinoma (SCC), hepatocellular carcinoma, cervical cancer, and epithelial ovarian cancer." (PMID 32093341, 2020). "In agreement with our data, CDKN3, along with other genes, has been found to be associated with lower survival of patients with lung adenocarcinomas." (PMID 23405241, 2013). "Similarly, there are other studies associating CDKN3 overexpression with poor survival in nasopharyngeal carcinoma, lung adenocarcinoma, breast, bladder, and cervical cancer." (PMID 37489460, 2023). "PRC1, TNS4, and CDKN3, which were used to construct the model, had significantly higher mRNA expression in lung adenocarcinoma samples than normal samples in the TCGA cohort." (PMID 40697537, 2025). "We found that overexpression of these 8 genes (CENPA, FAM83D, KNSTRN, CDKN3, CCNB1, CDK1, and CCNA2) is significantly associated with poor survival of lung adenocarcinoma patients (p-value < 0.05)." (PMID 36291764, 2022). "Upregulation of CDKN3 is considered to be a key factor in promoting tumor cell proliferation and malignant transformation in ovarian cancer, cervical cancer, lung adenocarcinoma and leukemia, and is a potential molecular target for antitumor therapy." (PMID 32963620, 2020). "CDKN3 is upregulated in 68.0% of the epithelial ovarian cancer samples and lung adenocarcinoma patients and is correlated with poor patient survival." (PMID 27818681, 2016). "CDKN3 overexpression is prognostic of poor overall survival in lung adenocarcinoma." (PMID 35178291, 2022). "The overexpression of CDKN3 in lung adenocarcinoma is not attributed to selective splicing or mutation but may be due to increased mitotic activity, thus acting as a tumor suppressor." (PMID 38965505, 2024). "The results showed that ACAN, CDKN3, GRIN2A, IL17A, KCNQ2, TIMP1, and UCHL1 were significantly up-regulated in lung adenocarcinoma cells." (PMID 36147496, 2022). "The intersections of LPS induction-related genes, lung adenocarcinoma differential genes, and univariate cox genes were obtained, and five genes (TNS4, PRC1, MKI67, CDKN3, BIRC5) were obtained, which were defined as the characteristic genes associated with LPS induction." (PMID 40697537, 2025). "The expression of LDHA, CDKN3, and SHC1 were significantly raised in lung adenocarcinoma compared to non-cancer cells, whereas BTK expression was higher in non-cancer than in cancer cells (Figures 8A2, B2, C2, D2)." (PMID 40182622, 2025). "In a word, our research shows that the expressions of key genes of sphingolipid metabolism, such as LDHA, CDKN3, SHC1 and BTK, are obviously different from those of non-cancerous tissues in lung adenocarcinoma, and can obviously affect the prognosis of LUAD patients." (PMID 40182622, 2025).
pancreatic cancer (17 papers, 2008 to 2025). "In vitro and in vivo research has revealed that cyclin-dependent kinase inhibitor 3 (CDKN3) is adversely associated with pancreatic cancer tissue prognosis." (PMID 35077391, 2022). "A study found a direct association between YY1 and CDKN3 in pancreatic cancer." (PMID 37682177, 2023). "Another study showed that a transcriptional regulator Yin Yang-1 (YY1) downregulated the expression of CDKN3 by directly binding to the promoter region of CDKN3 in pancreatic cancer cells." (PMID 38356706, 2024). "Interestingly, CDKN3, as an RNA methylation related isomer of pancreatic cancer, has been proved to be involved in immune infiltration." (PMID 38720365, 2024). "Additionally, cell function investigations suggested that knockdown of CDKN3 remarkably inhibited the proliferation and migration of pancreatic cancer cells." (PMID 35864471, 2022). "Additionally, PSMD12 interacts with CDKN3 and facilitates the progression of pancreatic cancer." (PMID 41444773, 2025).
cervical cancer (15 papers, 2010 to 2025). A primary or metastatic malignant neoplasm involving the cervix. "CDKN3 has been reported to be overexpressed in glioma and cervical cancer, and its over-expression is associated with inferior survival." (PMID 37007961, 2023). "It is important to emphasize that more studies are needed to completely understand the role of CDKN3 in cervical cancer and determine if it is associated with low survival of patients with CC in other populations as well." (PMID 26372210, 2015). "This is the first report in which CDKN3 was associated with cervical cancer." (PMID 23405241, 2013). "Of the top 10 ranked upregulated genes, 2 have not been previously reported as associated with cervical cancer (NUSAP1, and CDKN3), while the other 8 have been associated with cervical cancer either scantly (SYCP2, PRC1, CCNB2 and CDC20) or widely (MKI67, CDKN2A, CDC2, and PCNA)." (PMID 23405241, 2013). "The cyclin-dependent kinase inhibitor 3 (CDKN3) gene, involved in mitosis, is upregulated in cervical cancer (CC)." (PMID 26372210, 2015). "Clarifying the role of CDKN3 in cervical cancer is important to design appropriate strategies to target CDKN3." (PMID 26372210, 2015). "Doubling time increased in cervical cancer cell lines transfected with specific siRNAs against CDKN3." (PMID 26372210, 2015). "CDKN3 gene expression decreased in cervical cancer cell lines transfected with specific siRNAs against CDKN3." (PMID 26372210, 2015). "There is also evidence to support that CDKN3 in cervical cancer (CC) can not only be used as a useful marker that survives and selects additional chemotherapy or specific targeted cancer treatment but also as a specific small drug for developing anti-CC potential target." (PMID 36147496, 2022). "In this work we identified 6 genes (PRC1, CCNB2, SYCP2 CDKN3, NUSAP1, and CDC20) associated with invasive cervical cancer that could be used either as markers for diagnosis or as therapeutic targets." (PMID 23405241, 2013).
melanoma (14 papers, 2009 to 2024). A malignant, usually aggressive tumor composed of atypical, neoplastic melanocytes. "Upon reviewing relevant databases, we noted a dearth of research exploring the prognostic implications of CDKN3 in bladder tumors, multiple myeloma, neuroendocrine tumors, and melanoma." (PMID 38720365, 2024). "We therefore validated that the gene expression of AURKA, CCNB1 and CDKN3 was upregulated upon UV-irradiation of Group 3 FM SF cultures and compared the expression of these genes in normal skin and melanoma tissue." (PMID 23371019, 2013).
ovarian carcinoma (14 papers, 2004 to 2026). A malignant neoplasm originating from the surface ovarian epithelium. "Likewise, in certain cancer types, including tumors of the breast, lung, and colon, high levels of CDK1 have also been associated with poor prognosis, while upregulation of CDKN3 has been underscored as an independent poor prognostic factor in ovarian cancer." (PMID 37509358, 2023). "For example, in a study conducted in ovarian cancer, CDKN3 protein was found to be overexpressed by 3.35-fold in epithelial ovarian cancer specimens compared to healthy ovarian epithelium, and this overexpression was correlated with lower patient survival." (PMID 38356706, 2024). "The authors further showed that inhibition of CDKN3 expression in an ovarian cancer cell line OVCAR3 inhibited cell growth and proliferation." (PMID 38356706, 2024). "Knock down of SMYD3 in ovarian cancer tissues leads to upregulation of CDKN2B (p15INK4B), CDKN2A (p16INK4), CDC25A and CDKN3 as members of cyclin-dependent kinase inhibitors (CDK)." (PMID 33333978, 2020). "Moreover, CDKN3 can act as a positive regulator of CDK and Cyclin in certain cancer type, including gastric cancer, ovarian cancer and esophageal cancer." (PMID 33468140, 2021).
hepatocellular carcinoma (13 papers, 2010 to 2024). A malignant tumor that arises from hepatocytes. "In order to understand the expression of CDKN3 in different tumours, Oncomine analysis was performed, and the results showed that CDKN3 was significantly elevated in anaplastic oligodendrocytoma, leukaemia, hepatocellular carcinoma and sarcoma." (PMID 32000807, 2020). "Meanwhile, Oncomine analysis showed that CDKN3 was significantly up-regulated in anaplastic oligodendrocytoma, leukaemia, hepatocellular carcinoma and sarcoma." (PMID 32000807, 2020). "Moreover, a study indicated that CDKN3 expression was negatively correlated with tumor staging, and CDKN3 inhibition promoted hepatocellular cancer cell survival and cisplatin tolerance." (PMID 37393234, 2023). "CDKN3 promotes tumorigenesis in ovarian, colorectal, and hepatocellular cancer." (PMID 26859141, 2016).
gastric cancer (12 papers, 2011 to 2024). A primary or metastatic malignant neoplasm involving the stomach. "Since depletion of NKX6.3 in gastric epithelial cell lines induced CNAs and abnormal expression of SORBS2, SPARCL1, DLGAP5, and CDKN3, we examined NKX6.3 expression and these genes’ CNAs and expression in gastric cancer tissues." (PMID 34893582, 2021). "The expression levels of CDKN3 and DLGAP5 were markedly increased, whereas those of SPARCL1 and SORBS2 were decreased in 60 human gastric cancers." (PMID 34893582, 2021). "In addition, the mRNA expression levels of CDKN3, DLGAP5, SPARCL1, and SORBS2 were positively correlated with CNAs in our gastric cancer samples." (PMID 34893582, 2021).
lung carcinoma (12 papers, 2012 to 2025). "In agreement with our data, upregulation of CDKN3 gene, together with other genes, has been associated with decreased survival of patients with lung cancer and astrocytoma." (PMID 26372210, 2015). "Although overexpression of CDKN3 has been associated with inhibition of cell proliferation in colon cancer cell lines, it has also been found to be overexpressed in breast, prostate, and lung cancers." (PMID 23405241, 2013). "CDKN3 may be involved in cell cycle regulation, and high expression of CDKN3 predicts poor prognosis in lung cancer patients." (PMID 36712848, 2022). "Immunohistochemical staining was utilized for identifying the expression of LDHA, CDKN3, SHC1, and BTK in 127 lung cancer samples." (PMID 40182622, 2025). "qRT-PCR confirmed that the expression level of CDKN3, MKI67, CEP55, SPAG5, AURKA, TOP2A were highly expressed in lung cancer tissues." (PMID 35178291, 2022). "A signature of genes including CDC20, CCNB1, CDC2, CDKN3, MAD2L1, PRC1 and RRM2, were prognostic for 5-year survival in over 400 lung cancer cases, and interestingly, CDC20, CDC2, CCNB1 were also highly overexpressed in the aggressive case." (PMID 22905093, 2012).
colorectal cancer (11 papers, 2011 to 2025). A primary or metastatic malignant neoplasm that affects the colon or rectum. "Yang and Sun showed the role of CDKN3 in cellular proliferation of colorectal cancer by examining the effects of CDKN3 siRNA on the SW480 cell line; it is associated with cell cycle progression and apoptosis." (PMID 37489460, 2023). "There have been studies using transcriptomics to determine that CDKN3 is a core gene for the prognosis of colorectal cancer." (PMID 38720365, 2024). "In our study using a different dataset, we found that the CDKN3 gene was highly expressed and less methylated in colorectal cancer patients compared to normal samples." (PMID 37489460, 2023).
glioma (11 papers, 2009 to 2025). A benign or malignant brain and spinal cord tumor that arises from glial cells (astrocytes, oligodendrocytes, ependymal cells). "The aberrant splicing of CDKN3 (cyclin-dependent kinase inhibitor 3) mRNA in human gliomas generated a dominant negative CDKN3 variant and the CDKN3 over expression correlated with decreased patient survival." (PMID 24475040, 2014). "Treatment with MNF also sensitized C6 glioma tumor xenograft to growth arrest via the downregulation of Galnt3 and other cell cycle regulators, such as Ccna2, Cdkn3, and Bub1b." (PMID 25505565, 2013). "CCNB1 and CDC2 play important roles in the proliferation of Glioma cells, the expression of PTTG1 is correlated with poor prognosis in Glioma patients, and aberrant splicing of CDKN3 increases proliferation and migration in Glioma cells." (PMID 21698123, 2011). "Finally, we visualized the close association between CDCA3 and common glioma cell cycle checkpoint markers, including CDK6, CDK4, CDK2, CDK1, CDKN3, and CDKN2C, using circos plots." (PMID 38728485, 2024). "After calculating the hazard ratio and confidence interval, we observed that 8 hub genes in hub network 1 were related to the poor prognosis of gliomas, including PBK, KIF2C, CENPE, KIF14, MND1, FAM83D, NEIL3, and CDKN3." (PMID 35387222, 2022).